MTOR (mechanistic target of rapamycin kinase)
Diseases named in the same sentence as MTOR in open-access papers (continued):
Sharing a sentence is not in itself a finding about the gene and the disease.
cancer (continued). "The mammalian target of rapamycin (mTOR) pathway is involved in various cellular processes and inhibition of mTOR signalling has been shown to extend life span in several different species, including yeast, flies, worms, and mice, in part by suppressing age related pathologies and cancer." (PMID 27036037, 2016). "Additionally, this article is designed to provide the clinician with current management approaches and encourage novel basic, translational, and clinical studies that could enhance the future care of patients with cancer who will receive mTOR inhibitors." (PMID 27334013, 2016). "Since the PI3K/akt/mTOR pathway and KRAS oncogene mutations all have roles in cancer cell metabolism, we investigated whether the activity of PI3K/akt/mTOR inhibitors (BEZ235 and BKM120) in cells harboring different KRAS status is related to their metabolic effect." (PMID 27283493, 2016). "Because cut-off definitions for positive mTOR expression varied notably from 5 % staining to 25 % staining of cancer cells between studies, an unavoidable deviation originated from heterogeneous criteria of evaluation could negatively affect the validity of pooled estimates." (PMID 27835987, 2016). "We then studied whether IKKα promotes Akt and mTOR activity in other mammalian cancer cell lines." (PMID 27027448, 2016). "Recent studies demonstrate that mTOR down-regulation may sensitize cancer cells to PARP inhibitors." (PMID 27555886, 2016). "In addition, determination of tumor DGKζ levels might be a useful biomarker in the selection of cancer therapy and to predict the effectiveness of mTOR inhibitors." (PMID 26302180, 2015). "Given the critical role of the PI3K/Akt/mTOR signaling pathway in cancer biology and the immunostimulatory effect of PI3K/Akt/mTOR inhibitors on DC-tumor hybrids, combination therapy may represent a promising and novel cancer vaccine with enhanced clinical impact." (PMID 26605345, 2015). "Therefore, disrupting the PI3K/Akt/mTOR pathway may be a potential way for cancer therapy, or at least helpful for increasing sensitivity to chemo and radio therapy." (PMID 25965911, 2015). "Furthermore, mTOR seems to have a stage-dependent impact, with the expression being higher in earlier stages of gastric carcinogenesis; however, our cohort mostly consisted of advanced stage cancers." (PMID 26652716, 2015). "Thus, inactivation of NR4A1 by the receptor antagonist DIM-C-pPhOH or the corresponding p-carboxymethyl analog (DIM-C-pPhCO2Me) decreases expression of genes associated with cell proliferation and survival, induces oxidative stress, and inhibits mTOR in cancer cell lines." (PMID 26035713, 2015). "Furthermore, the pharmacological inhibition of mTOR can lead to the up-regulation of MAPK through the p70S6K-PI3K-Ras signaling cascade modulated by IRS-1 in human cancer, indicating the possibility of the existence of the interplay of mTOR and ERK in OA chondrocytes." (PMID 26247939, 2015). "Metformin attenuates cancer growth indirectly through reduction in serum insulin and IGF–1 concentration caused by improvement in insulin sensitivity, and directly through cell cycle arrest and inhibition of mammalian target of rapamycin (mTOR) following AMPK activation." (PMID 26439622, 2015). "While the beneficial effects of mTOR inhibition by rapamycin on aging and age-related disease have been reproducibly demonstrated, there has been recent debate over whether the anti-cancer effects of rapamycin may account for the lifespan benefits in the mouse model." (PMID 26257774, 2015).
cancer (continued). "Hyperactivation of PI3K-AKT signaling in cancer has formed the underlying basis for targeted therapies against this cascade that are currently in clinical development, including dual PI3K-mTOR inhibitors, PI3K inhibitors, AKT inhibitors, and mTOR complex catalytic site inhibitors." (PMID 26125440, 2015). "In addition, PI3K/AKT/mTOR signaling also plays an important role in angiogenesis regulation in various cancers by increasing VEGF production in endothelial cells as well as in cancer cells." (PMID 26299806, 2015). "Therefore, we employed Western blot to test whether the PI3K/AKT/mTOR signal pathway was involved in the RY-2f-mediated anti-cancer effects." (PMID 26325371, 2015). "Thus, mTOR has also become a potential therapeutic target in anti-cancer therapies." (PMID 26301867, 2015). "Therefore, the mTOR signaling pathway provides a new strategy for cancer therapy." (PMID 25654224, 2015). "Given that PI3K/mTOR inhibitors repress aerobic glycolysis in EGFR-mutated LAD cells, further studies are warranted to understand how cancer cell metabolism is regulated and to develop more effective therapeutic agents specifically targeted to the metabolic pathways that can limit cancer growth." (PMID 26023239, 2015). "Nevertheless, studies of extraordinary responses to rapalogs suggest that routine screening of cancer patients for alterations in the mTOR pathway may be helpful to identify a subset of patients who are much more likely to respond to mTOR-pathway targeted therapies than other patients." (PMID 26137524, 2015). "Further work also suggests that this abnormal mTOR activity induces a peculiar osteotropic phenotype of BC cells, probably involved in skeleton colonization, that could ultimately be modulated by inhibiting this pathway, as demonstrated in other cancers." (PMID 26468083, 2015). "It was demonstrated that ROS can induce autophagy through several distinct mechanisms involving Atg4-Atg8/LC3, Beclin-1, PI3K-Akt-mTOR, catalase, and the mitochondrial electron transport chain, which leads to both cell-survival and cell-death responses and could be selective toward cancer cells." (PMID 25891311, 2015). "It is known that the inhibition of the mTOR pathway could trigger cancer autophagy." (PMID 26098947, 2015). "Thus, autophagy inhibitors could potentially overcome resistance to mTOR-targeted therapies for cancer." (PMID 26134285, 2015). "Rapamycin may be effective in cancer inhibition at doses lower than that necessary for robust inhibition of normal mTOR signaling, and rapamycin diet at the standard ITP dose of 14 PPM may have robust anti-cancer effects with only a relatively modest influence on other age-related pathologies." (PMID 26257774, 2015). "Furthermore, Mammalian target of rapamycin (mTOR), a serine/threonine kinase which is a key player in the PI3K/Akt pathway, acting both up and downstream of Akt has also been linked with a variety of cancers when dysregulated." (PMID 26301867, 2015). "Moreover, many preclinical and clinical studies support that mTOR inhibitors, such as sirolimus (rapamycin) and their derivatives may improve cancer treatment." (PMID 26569621, 2015). "Therefore, it seems essential to target both the mTOR complexes for desired anti-cancer effects." (PMID 25741318, 2015). "Therefore, mTOR inhibitors could suppress the invasion and metastasis of cancer cells through increasing the cell-cell adhesions." (PMID 25996501, 2015). "In this retrospective study we therefore hypothesized that the basal values and changes in metabolic assessment before and during therapy with everolimus could reflect the inhibition of mTOR in the cancer cell and could serve as predictors of clinical efficacy of treatment with everolimus in mRCC." (PMID 25885920, 2015).
cancer (continued). "Imasmuch as many cancers exhibit mTOR hyperactivation, the identification of previously unappreciated proteins needed for maintenance of mTORC1 activity may provide new drug targets and lead to the development of beneficial therapies for tumors sensitive to mTOR inhibition." (PMID 25790369, 2015). "Because as we all know, the PI3K/AKT/mTOR signaling pathways not only play an important role in normal cellular processes such as proliferation, survival, and differentiation, but also frequently deregulated in cancer cells and its constitutive activity strongly contributes to the oncogenic process." (PMID 25965911, 2015). "Thus, mTOR inhibitors such as temsirolimus and Torin1 may have a broad application in the treatment of cancer." (PMID 26460955, 2015). "Importantly, fasting and calorie restriction inhibits mTOR, and as a result fasting may improve cancer therapy." (PMID 25760074, 2015). "In addition, mTOR kinase inhibitors are currently in many human cancer clinical trials." (PMID 26308575, 2015). "Further studies may be warranted to elucidate potential targeted therapeutics against mutations in the mTOR pathway and the receptor tyrosine kinase family in MSI-H CRCs as well as the benefit of anti-PD-1 immunotherapy in hypermutated MSS CRCs or other cancers." (PMID 26517354, 2015). "Our results from this study suggest that metformin may suppress cancer cell growth via inhibition of mTOR, but the differential basal autophagy and feedback activation of Akt induced by metformin in certain cancer cells may contribute to resistance to metformin-induced inhibition of cell growth." (PMID 26111001, 2015). "Thus, the concomitant dual inhibition of PI3K/mTOR or Akt/mTOR may be a solution to these feedback loops and provide a superior strategy for overcoming development of resistance of cancer cells to targeted therapy." (PMID 24969552, 2014). "It is not excluded that although primary mTOR mutations are barely observed in human cancers, the mTOR kinase could be hit by a secondary or even a de novo gene mutation in response to therapy as a self-defense mechanism." (PMID 24393708, 2014). "However, further in-depth investigation is required to explore whether NEDD4 promotes cell invasion and metastasis in other human cancers, and its dependence on activation of the mTOR/Akt oncogenic signaling pathway." (PMID 24657926, 2014). "The phosphatidylinositol 3-kinase (PI3K)/AKT/mTOR signaling pathway, which drives cell proliferation, motility, and survival, is frequently hyperactivated in a variety of malignancies, and inhibition of this pathway has been considered an appropriate approach for cancer therapy." (PMID 25098767, 2014). "Therefore, we investigated the FBXW7 mutational status and clinical and demographic characteristics of patients with advanced cancer referred to our Phase I Clinical Trials Program and the outcomes of such patients treated with agents targeting the mTOR pathway." (PMID 24586741, 2014). "This evaluation of cognitive functioning and brain metabolic activity following everolimus treatment might help to elucidate the physiopathology of the neurological alterations observed among cancer patients treated with targeted therapies such as mTOR inhibitors." (PMID 25436776, 2014). "However, the crosstalk between Shh and mTOR pathways is known to exist in other cancers." (PMID 25432075, 2014). "However, in previous investigations using cancer cell lines, the inhibition of mTOR not only showed reduced activation in respect of cell proliferation and migration but also decreased activity of PI3K/Akt itself, suggesting susceptibility of even upstream mediators." (PMID 24586308, 2014). "Thus, mTOR or NOTCH1 inhibitors could be effective in ameliorating the consequences of FBXW7 inactivation in cancer cells." (PMID 25593991, 2014). "Besides the functional roles of mTORC1 and mTORC2, our study describes a novel function of mTOR that might be critical for a high growth rate of cancer cells." (PMID 25294810, 2014).
cancer (continued). "Since multiple components of the PI3k/Akt/mTOR pathway are deregulated in a wide variety of solid tumors, considerable attention has been focused on the biochemical and genetic characterization of this pathway in cancer and on developing new drugs to inhibit it." (PMID 24497570, 2014). "Therefore, we favor the idea that mTOR might be a versatile multitasker which takes on cancer and other pathologies." (PMID 25115395, 2014). "Several reports have indicated that mTOR inhibition may enhance the antitumor effects of cytotoxic agents in an additive or synergistic manner when tested in vitro and in vivo models of multiple types of human cancers." (PMID 24916546, 2014). "Metformin may exhibit inhibitory effects on cancer cells by inhibiting the mTOR signaling pathway." (PMID 24774412, 2014). "In this study, our CaP-RR cells with induced EMT and enriched CSCs7 could be successfully treated with combination of dual PI3K/mTOR inhibitors and RT, suggesting that this combination therapy may target CSCs (‘root' of cancer recurrence) to overcome radioresistance and prevent metastasis." (PMID 25275598, 2014). "That is a strong possibility given that several oncogenes are regulated by FBXW7, including MYC, Notch, JUN and cyclin E. Thus, targeting different pathways in addition to the mTOR pathway might be necessary to effectively kill cancer cells in tumors driven by FBXW7 alterations." (PMID 24586741, 2014). "Similarly, very few incidences of cancer have been reported in grizzly bears, or even bears in general, that, like the naked mole-rat, may downregulate mTOR signaling, albeit seasonally." (PMID 25553771, 2014). "Therefore, we detected the changes in active status of mTOR in OA-treated cancer cells." (PMID 24626155, 2014). "Therefore, some hypothesize that cancers may suffer from an oncogenic “addiction” to the constant activation of the PI3K/Akt/mTOR pathway." (PMID 25334061, 2014). "Thus, it may be proposed that long-term administration of mTOR inhibitors occurring in cancer treatment could affect brain functions involved in cognition and/or metabolism." (PMID 25436776, 2014). "Metformin may exhibit inhibitory effects on cancer cells by inhibiting mTOR signaling pathway." (PMID 24774412, 2014). "Antineoplastic effects have also been proposed for mTOR inhibitors and everolimus marketed as Afinitor (Novartis Pharma AG; Basel, Switzerland) is already approved for a number of cancer indications and may have further relevance in the setting of posttransplant malignancy and HCC recurrence." (PMID 24719752, 2014). "While it is well documented that cytokines play an important role in anti-cancer immunity, our data provide the underlying explanation for failure of agents targeting PI3K pathway in clinical trials and a rationale for the combined treatment with PI3K/Akt/mTOR inhibitors and immunological therapy." (PMID 24718556, 2014). "Therefore, the mTOR inhibitor is hypothesized to represent a promising therapeutic agent for various types of carcinomas." (PMID 24348822, 2014). "Although the molecular target of coibamide A has still to be established, our findings provide insight into a new marine natural product structure that may be an invaluable tool for the study of both mTOR-independent autophagy and cell death signaling in apoptosis-resistant cancer cells." (PMID 23762328, 2013). "Finally, our findings may be relevant to other diseases in which Rapamycin and its analogs are currently being used therapeutically, including cancer, for which there are currently more than 100 active cancer clinical trials using mTOR inhibitors." (PMID 23555865, 2013).
cancer (continued). "Taken together, this study reveals a novel mechanism by which IGF-1 activates MDM2 via the mTOR pathway, and that pharmacologic inhibition of mTOR combined with chemotherapy may be more effective in treatment of a subset of cancers harboring increased MDM2 activation." (PMID 23638184, 2013). "Thus, inhibition of mTOR pathway to induce apoptosis is an attractive target for cancer therapy." (PMID 23818927, 2013). "Thus, the combined inhibition of both PI3K and mTOR might be necessary for effective treatment of cancer." (PMID 24042258, 2013). "Therefore, the PI3K/Akt/mTOR pathway represents an attractive target for cancer therapy." (PMID 24237791, 2013). "Therefore, it was speculated that mTOR is a possible driver gene in carcinogenesis, and a promising target point and prognosis marker in cancer treatment as well." (PMID 23940798, 2013). "GOLPH3, which encodes a peripheral membrane protein of the Golgi stack and may have a regulatory role in Golgi trafficking, was recently shown to enhance growth-factor-induced mTOR signaling and consequently alter response to rapamycin, an mTOR inhibitor, in cancer cells." (PMID 23433318, 2013). "Therefore, studies targeting mTOR for cancer therapy have received attention in recent years." (PMID 23874880, 2013). "Furthermore, mTOR plays a key role in the phosphatidylinositol 3-kinase (PI3K)/AKT pathway which is frequently dysregulated and implicated in the growth and progression in several cancers, making it an attractive therapeutic target." (PMID 23520486, 2013). "The impact of mTOR on cellular metabolism, the immune microenvironment, cell proliferation and differentiation, and cancer metabolism provides an attractive therapeutic target for metabolic diseases as well as cancer early detection and therapeutic interventions." (PMID 23783557, 2013). "Recent in vitro studies showing increased sensitization of cancers with defects in DNA homologous recombination (as seen in BRCA1/2 deficient cancers), to PARP inhibition by targeting of PIK3CA suggest that PIK3CA/mTOR pathway interactions result in homologous recombination steady state." (PMID 23971979, 2013). "Therefore, mTOR inhibitors have been proposed for the treatment of cancer." (PMID 24179542, 2013). "Indeed, we have others have shown that activated AKT/mTOR induces SCD1 expression in cancers." (PMID 24069385, 2013). "It has been documented that the upregulation of LAT1 expression in cancer cells not only induces an increase in the transportation of amino acids, particularly essential amino acids such as leucine, but also activates the mammalian target of rapamycin (mTOR) signaling pathway." (PMID 23946786, 2013). "Hence, targeting PI3K/Akt/mTOR signaling with small molecule inhibitors may improve cancer patient outcome." (PMID 22564882, 2012). "The mTOR is involved in several important intracellular signal transduction pathways that regulate cell survival, hyperplasia, apoptosis, and other important physiological functions critical to tumorigenesis and cancer development, thus providing as a potential anti-cancer therapy." (PMID 22709792, 2012). "Since mTOR is frequently deregulated in cancer and because, as mentioned, piceatannol acts as a potent kinase inhibitor, it is of interest to determine whether piceatannol might affect mTOR activity/expression and in turn disrupt mTOR-mediated signaling events." (PMID 22567414, 2012). "Furthermore, the activation of the mTOR pathway is the most universal alteration in cancer." (PMID 23117593, 2012). "Indeed, using the mTOR inhibitor, rapamycin, yields promising results for multiple human cancers." (PMID 22666248, 2012). "Therefore, mTOR is an appealing therapeutic target and mTOR inhibitors, including the rapamycin analogues deforolimus, everolimus and temsirolimus, are submitted to clinical trials for treating multiple cancers, alone or in combination with inhibitors of other pathways." (PMID 22408430, 2012).